LINC01003 (long independently transcribed non-coding RNA 1003)
Gene: Long non-coding RNA gene on chromosome 7 (152,463,786 to 152,465,551, forward strand). Ensembl gene ENSG00000261455.
Diseases named in the same sentence as LINC01003 in open-access papers:
LINC01003 is named in the same sentence as 6 diseases in open-access papers, as found by Europe PMC text mining. Sharing a sentence is not in itself a finding about the gene and the disease. The quoted sentences say what the papers report.
glioma (2 papers, 2023 to 2024). A benign or malignant brain and spinal cord tumor that arises from glial cells (astrocytes, oligodendrocytes, ependymal cells). "Here, we examined the potential functions of a lncRNA, LINC01003, in glioma and characterized the underlying molecular mechanisms." (PMID 37270527, 2023). "Taken together, these results suggested that LINC01003 expression was upregulated in glioma and positively associated with poor prognosis." (PMID 37270527, 2023). "The functions of LINC01003 in glioma growth and migration were assessed by loss-of-function experiments in vitro and in vivo." (PMID 37270527, 2023). "Collectively, these data suggested that METTL3-mediated m6A modification is associated with the upregulation of LINC01003 in glioma." (PMID 37270527, 2023). "In this study, we demonstrated that lncRNA LINC01003 is highly expressed in glioma and is associated with the poor clinical prognosis of glioma patients." (PMID 37270527, 2023). "A loss-of-function assay indicated that LINC01003 can trigger the migration of glioma cells in vitro." (PMID 37270527, 2023). "Importantly, we found that higher LINC01003 expression level is associated with poor prognosis in glioma patients." (PMID 37270527, 2023). "Previous studies have demonstrated that upregulation of LINC01003 plays a role in regulating cell migration through the CAV1/FAK signaling pathway in glioma." (PMID 39456519, 2024). "Then the m6A modification level of LINC01003 in glioma cells was determined by RNA immunoprecipitation and RT-qPCR assays." (PMID 37270527, 2023). "We confirmed that LINC01003 promotes glioma proliferation and migration through in vitro and in vivo functional assays." (PMID 37270527, 2023). "The RNA m6A methyltransferase METTL3 was shown to epigenetically mediate the upregulation of LINC01003 in glioma." (PMID 37270527, 2023). "We observed that LINC01003 expression was significantly upregulated in glioma patients compared with normal controls." (PMID 37270527, 2023). "We found that LINC01003-silenced glioma cells showed changes in the distribution of the cell cycle, with increased arrest at S phase and decreased proportion of G0/G1 phase." (PMID 37270527, 2023). "The GEPIA2 database showed that LINC01003 expression in GBM (glioblastoma multiforme) or LGG (lower grade glioma) is significantly higher than in normal brain tissues." (PMID 37270527, 2023). "To determine the role of the LINC01003/CAV1 axis in glioma, we employed functional rescue experiments in vitro and in vivo." (PMID 37270527, 2023). "EdU assays indicated that LINC01003 knockdown significantly inhibited DNA replication in glioma cells." (PMID 37270527, 2023). "Genetic addition of CAV1 alleviated the inhibitory effect of LINC01003 deficiency on the migration and p-FAK levels of glioma cells." (PMID 37270527, 2023). "Bioinformatics analysis and RNA immunoprecipitation (RIP) assays were used to explore the mechanism underlying the N6-methyladenine (m6A) modification-dependent upregulation of LINC01003 in glioma." (PMID 37270527, 2023). "In this study, we identified a new lncRNA, LINC01003, which showed a significant trend of increased expression in glioma tissues." (PMID 37270527, 2023). "To further verify the function of LINC01003 in glioma, we determined the effect of LINC01003 on cell proliferation and the cell cycle by silencing LINC01003 in U87MG and U251 glioma cells using lncRNA smart silence." (PMID 37270527, 2023). "This study characterized LINC01003 as a lncRNA that contributes to tumorigenesis in glioma and demonstrated that the LINC01003-CAV1-FAK axis serves as a potential therapeutic target for glioma." (PMID 37270527, 2023). "An anti-m6A RIP assay combined with RT-qPCR indicated that the m6A modification of LINC01003 was remarkably decreased in LINC01003-silenced glioma cells." (PMID 37270527, 2023). "Collectively, this result indicated that LINC01003 knockdown inhibits the migration of glioma cells." (PMID 37270527, 2023).
glioma (continued). "Functionally, LINC01003 knockdown inhibited the cell cycle and cell proliferation and migration in glioma cells." (PMID 37270527, 2023). "Based on these results, LINC01003 may represent a predictor of prognosis and potential therapeutic target for glioma therapy." (PMID 37270527, 2023). "LINC01003 knockdown inhibited glioma tumor volume and weight in nude mice." (PMID 37270527, 2023). "Higher LINC01003 expression predicted shorter overall survival time in glioma patients." (PMID 37270527, 2023). "In conclusion, these results suggested that knockdown of LINC01003 inhibits glioma growth in vivo." (PMID 37270527, 2023). "In addition, LINC01003 expression in glioma cell lines was significantly higher than in normal HEB cells." (PMID 37270527, 2023). "Furthermore, knockdown of LINC01003 significantly suppressed the proliferation of glioma cells in vitro and tumorigenesis in vivo." (PMID 37270527, 2023). "Thus, clarifying the functions and mechanism of LINC01003 will provide anti-metastatic therapies in glioma." (PMID 37270527, 2023). "We found that LINC01003 depletion significantly reduced FAK phosphorylation in glioma cells." (PMID 37270527, 2023). "Our findings suggested that LINC01003 may be a crucial effector molecule that induces EMT in glioma." (PMID 37270527, 2023). "LINC01003 expression was upregulated in glioma cell lines and tissues." (PMID 37270527, 2023). "To determine the upstream mechanism of LINC01003 overexpression in glioma, we investigated whether m6A methylation regulates LINC01003 expression." (PMID 37270527, 2023). "Our results demonstrated the pro-metastatic function of LINC01003 in the diffusion of glioma cells." (PMID 37270527, 2023). "In glioma, LINC01003 is highly expressed in glioma stem cells." (PMID 37270527, 2023). "Our sequencing data suggested that LINC01003 mediates the expression of focal adhesion-related genes, indicating that LINC01003 might regulate focal adhesion in glioma cells." (PMID 37270527, 2023). "Therefore, our study indicated that LINC01003 is a positive regulator in the CAV1/FAK signaling pathway in glioma cells." (PMID 37270527, 2023). "Furthermore, we showed that LINC01003 can modulate an CAV1/focal adhesion kinase (FAK) signaling pathway in glioma." (PMID 37270527, 2023). "Thus, we speculated that m6A modifications were responsible for the upregulation of LINC01003 in glioma." (PMID 37270527, 2023). "Moreover, METTL3-mediated m6A modification may increase LINC01003 expression and function in glioma cells." (PMID 37270527, 2023). "From this report we speculated that LINC01003 would play a critical role in glioma tumorigenesis." (PMID 37270527, 2023). "Interestingly, we identified a new signaling axis, LINC01003/CAV1/FAK, through which LINC01003 regulates focal adhesion in glioma." (PMID 37270527, 2023). "In glioma cells, knockdown of METTL3 significantly reduced the expression of LINC01003." (PMID 37270527, 2023). "We found that METTL3 mediates the expression and m6A modification of LINC01003, suggesting that METTL3-mediated m6A modification may be responsible for the upregulation of LINC01003 in glioma." (PMID 37270527, 2023).
multiple myeloma (2 papers, 2022 to 2023). "A recent study demonstrated that LINC01003 acts as a suppressor in multiple myeloma." (PMID 37270527, 2023). "In multiple myeloma, LINC01003 behaves as a tumor suppressor genomic element." (PMID 35982973, 2022).
hypophosphatasia (1 paper, 2023). Hypophosphatasia (HPP) is a rare heritable metabolic disorder characterized by defective mineralization of bone and/or teeth in the presence of reduced activity of unfractionated serum alkaline phosphatase (ALP). "Finally, LINC01003 was found to correlate with Hypophosphatasia, and from the coefficient of each RNA, we know that LINC01003 plays an auxiliary predictive role." (PMID 37007132, 2023).
tumor (3 papers, 2022 to 2024). "The violin plot shows significant expression of LINC01003 in malignant cells, compared to other cell types, indicating its potential role in tumor progression." (PMID 38849442, 2024). "The xenografts result in nude mice further indicated that overexpression of CAV1 partially relieved the inhibition of tumor formation induced by knockdown of LINC01003 in vivo." (PMID 37270527, 2023). "The results indicate that LINC01003 is differentially expressed, with notable high expression in monocytes/macrophages and endothelial cells across several datasets, suggesting its potential involvement in these cell types within the NSCLC tumor microenvironment." (PMID 38849442, 2024).
cancer (2 papers, 2023 to 2024). A tumor composed of atypical neoplastic, often pleomorphic cells that invade other tissues. "However, the impact of GATA transcription factors on LINC01003 regulation has not been explored until now in any cancer type." (PMID 39456519, 2024). "Therefore, reduced levels of LINC01003 might play a crucial role in the dysregulated inflammation that could occur in response to TLR9 stimulation, particularly in situations where RBC-TLR9 levels are reduced due to treatments or cancer." (PMID 38203297, 2023).
LINC01003 also shares sentences with these, for which no sentence is quoted: glioblastoma multiforme (1 paper).